KRT81 (keratin 81)
Diseases named in the same sentence as KRT81 in open-access papers:
KRT81 is named in the same sentence as 44 diseases in open-access papers, as found by Europe PMC text mining. Sharing a sentence is not in itself a finding about the gene and the disease. The quoted sentences say what the papers report.
breast carcinoma (17 papers, 1998 to 2025). "Genes identified included novel genes such as HPGD, FASN and KRT81, as well as SCIN and TPM1 which have already been confirmed in acquired drug resistance mechanisms associated with HER2-positive breast cancer." (PMID 40946111, 2025). "Herein, a novel biomechanical mechanism is described by which ectopic expression of a truncated isoform of keratin 81 (tKRT81) promotes breast cancer metastasis." (PMID 37949677, 2024). "KRT81, a hair keratin, has become a biomarker of breast cancer and was revealed to promote cancer cell migration and invasion." (PMID 35403268, 2022). "The finding of increased expression of KIAA1199, GDF15 and KRT81 in our FSCN1CON compared to FSCN1KD TNBC is consistent with its over-expression in this breast cancer subtype and promotion of their migration." (PMID 34959629, 2021). "Breast carcinomas ectopically express KRT81, and in the present study we have observed KRT81 expression in lung tumor tissue by immunohistochemistry." (PMID 21799879, 2011). "KRT81 (Keratin 81), a member of the type II keratin family, is involved in cytoskeleton formation and resistance to mechanical stress, and plays a role in the regulation of diseases such as squamous cell lung carcinoma and breast cancer." (PMID 40519934, 2025). "KRT81 was identified in several breast cancer studies as well." (PMID 37949677, 2024). "Here, it is shown that ectopic expression of a truncated isoform of keratin 81 (tKRT81) in breast cancer is upregulated in metastatic lesions compared to primary tumors and patient‐derived circulating tumor cells, and is associated with more aggressive subtypes." (PMID 37949677, 2024). "KRT81 has also been shown to contribute to breast cancer cell migration and invasion." (PMID 37754243, 2023). "However, it was reported that KRT81 is expressed in clinical specimens from patients with breast cancer." (PMID 35186034, 2022). "Besides, keratin 81 (KRT81), a type II hair keratin, has been reported to be over-expressed in the breast cancer cells and contributed to their invasiveness." (PMID 33708105, 2020). "Transcriptomic analysis revealed upregulation of macrophage activation markers, genes such as S100A8, S100A2, KRT81, KRT6C, MARCO and MMP1, as well as processes related to keratinization and the formation of a cornified envelope in breast cancer cells." (PMID 41073799, 2025). "This same expression pattern was observed in some commonly used breast cancer cell lines (MCF7, MDA‐MB‐231, MDA‐MB‐361), whereas full‐length KRT81 was normally expressed in skin cells." (PMID 37949677, 2024). "The 3 pairs, corresponding to discoidin, CUB and LCCL domain containing 2 (DCBLD2, NM_080927.3), matrix metallopeptidase 24 (MMP24, NM_006690.3) and keratin 81 (KRT81, NM_002281.3) had their expression interrogated in 16 breast cancer cell lines and ten solid primary breast tumours." (PMID 19615061, 2009). "Importantly, in comparison to other types of breast cancer, the hazard ratio of KRT81 for TNBC was the highest, suggesting that KRT81 could be a valuable prognostic factor for TNBC." (PMID 38778753, 2024).
hepatocellular carcinoma (3 papers, 2015 to 2025). A malignant tumor that arises from hepatocytes. "To test the seeded aggregation of KRT8, we aggregated monomeric KRT81–90 in the presence of liver tissue extracts from people with either ASH or hepatocellular carcinoma (HCC)." (PMID 35637421, 2022).
melanoma (3 papers, 2024). A malignant, usually aggressive tumor composed of atypical, neoplastic melanocytes. "KRT81 was originally described to be involved in hair follicle formation and growth, but was since then also linked to cancers, including non-Hodgkin lymphoma and melanoma." (PMID 39169943, 2024).
monilethrix (3 papers, 2011 to 2022). Monilethrix is a rare genodermatosis characterized by a hair shaft dysplasia resulting in hypotrichosis. "Mutations in KRT81 have been described in monilethrix, a condition in which patients develop diffuse hypothrichosis." (PMID 26892682, 2016). "In this study, we have identified a Chinese family with monilethrix, and sequenced three keratin genes (KRT81, KRT83, and KRT86) of the subjects to elucidate the underlying molecular basis of this disorder." (PMID 23554671, 2011). "Specifically, mutations in the 1A and 2B domains of KRT81, KRT83, and KRT86 resulted in Monilethrix, a rare monogenic hair loss disorder 28,35." (PMID 35145093, 2022). "Interestingly, mutations in type II hard and soft hair keratins (KRT75, KRT81,83,85,86), but not type I hair keratins (KRT25-28, KRT31-40), have reported associations with other genetic hair disorders such as Monilethrix, pseudofolliculitis barbae, and hair ectodermal dysplasia." (PMID 35145093, 2022).
prostate carcinoma (3 papers, 2011 to 2024). A carcinoma that arises from epithelial cells of the prostate gland. "Among others, keratin 81, CrkII, IL-1β, and cathepsin C were identified as proteins directly or indirectly targeted by CA2-2 in human prostate cancer cells." (PMID 38248645, 2023).
lung adenocarcinoma (2 papers, 2024). A carcinoma that arises from the lung and is characterized by the presence of malignant glandular epithelial cells. "Concurrently, we will delve into the interactions between FSTL3 and other pertinent genes, such as KRT6A, VEGFC, KRT14, KRT17, SNORA12, and KRT81, to enhance our understanding of its role in lung adenocarcinoma progression and to pinpoint novel therapeutic targets." (PMID 38240936, 2024). "The prognosis of patients with lung adenocarcinoma was significantly affected by six genes (KRT6A, VEGFC, KRT14, KRT17, SNORA12, and KRT81) related to FSTL3." (PMID 38240936, 2024).
lung carcinoma (2 papers, 2017 to 2025). "KRT81, SPP1, PCDH7, SLC2A1, and TET1 are associated with poor prognosis and survival outcomes, providing novel insights for exploring lung cancer biomarkers." (PMID 41415280, 2025). "Genes KRT81, SPP1, PCDH7, SLC2A1, and TET1 were significantly upregulated in tumor tissues and associated with poor prognosis and survival, providing insights for exploring lung cancer biomarkers in future studies." (PMID 41415280, 2025).
lymphoma (2 papers, 2011 to 2014). A malignant (clonal) proliferation of B- lymphocytes or T- lymphocytes which involves the lymph nodes, bone marrow and/or extranodal sites. "The studies in lymphomas did not attempt to verify whether rs3660 in KRT81 affects miRNA binding and what are the functional consequences of the polymorphism." (PMID 25421940, 2014).
multiple myeloma (2 papers, 2014 to 2024). "The C allele of rs3660 in KRT81 reduced significantly the protein level in luciferase reporter assay in one of two myeloma cell lines (RPMI-8226)." (PMID 25421940, 2014). "Furthermore, a significant decrease of the proliferation rate of RPMI-8226 cells was observed upon silencing of the KRT81 gene, which indicates the possible mechanism underlying the better prognosis in myeloma patients carrying the CC genotype of KRT81_rs3660." (PMID 25421940, 2014).
pancreatic ductal adenocarcinoma (2 papers, 2024 to 2026). An infiltrating adenocarcinoma that arises from the epithelial cells of the pancreas. "Pancreatic ductal adenocarcinoma (PDAC) subtyping typically relies on immunohistochemistry (IHC) staining for critical markers like HNF1A and KRT81, a labor‐intensive manual staining process that introduces variability." (PMID 41188199, 2026). "For pancreatic ductal adenocarcinoma (PDAC), two IHC markers, hepatocyte nuclear factor‐1A (HNF1A) and cytokeratin‐81 (KRT81), have emerged as practical surrogates for defining relevant PDAC subgroups." (PMID 41188199, 2026).
squamous cell carcinoma (2 papers, 2011 to 2013). A carcinoma arising from squamous epithelial cells. "Additionally, the prognostic value of KRT81 rs3660 polymorphism was more marked in squamous cell cancer." (PMID 23613771, 2013). "Immunohistochemical analyses in 80 lung specimens showed that 95% of squamous cell carcinomas were positive for KRT81, compared to only 19% of adenocarcinomas (P<0.0001)." (PMID 21799879, 2011). "Since significant differences in TTR were found according to KRT81 rs3660 genotype, we further examined the effect of this genotype on the sub-groups of patients with adenocarcinoma and squamous cell carcinoma." (PMID 21799879, 2011). "KRT81 showed a clear positive staining in squamous cell carcinomas (95% positive), whereas 81% of adenocarcinomas were negative." (PMID 21799879, 2011). "Interestingly, in the sub-group analyses of TTR according to histological sub-type, the effect of the KRT81 rs3660 genotype on recurrence was more pronounced in patients with squamous cell carcinoma." (PMID 21799879, 2011). "In order to further explore this marked prognostic value of the KRT81 rs3660 genotype in squamous cell carcinoma, we analyzed KRT81 expression by immunohistochemistry in 42 squamous cell carcinoma, 33 adenocarcinoma and 2 adenosquamous carcinoma samples and in three normal lung tissue samples." (PMID 21799879, 2011). "Furthermore, the prognostic value of the KRT81 rs3660 genotype was more marked in squamous cell carcinoma, indicating that KRT81 may be a novel immunohistochemical marker for squamous cell carcinoma of the lung." (PMID 21799879, 2011). "In addition, we have found that KRT81 may well be a new immunohistochemical marker of squamous cell carcinoma." (PMID 21799879, 2011). "Our findings indicate that SNPs in KRT81 and XPO5 could prove to be useful biomarkers for individualizing therapy in NSCLC patients and that KRT81 may be a novel immunohistochemical marker of squamous cell carcinoma, providing a new diagnostic tool to be used in therapeutic decision-making." (PMID 21799879, 2011). "When patients were divided into sub-groups according to histology, the effect of the KRT81 rs3660 genotype on TTR was significant in patients with squamous cell carcinoma (P = 0.004) but not in those with adenocarcinoma." (PMID 21799879, 2011).
squamous cell lung carcinoma (2 papers, 2011 to 2025). A carcinoma arising from squamous bronchial epithelial cells. "Moreover, KRT81 has emerged as a promising immunohistochemical marker for the identification of squamous cell lung carcinoma." (PMID 21799879, 2011).
autoimmune pancreatitis (1 paper, 2023). "So far, models were proposed for PDAC diagnosis (vs autoimmune pancreatitis) or to predict simpler molecular labels that were reported to impact survival in PDAC, such as KRT81 positivity by immunohistochemistry." (PMID 37311751, 2023).
cholesteatoma (1 paper, 2012). A pathologic process characterized by the proliferation of keratinizing squamous epithelium resulting in the accumulation of keratin and cells in the middle ear and/or mastoid. "The analysis of the cytokeratin-expression revealed an up-regulation of Keratin 6 A and B, Keratin 18, Keratin 19 and Keratin 81 in cholesteatoma compared to normal skin." (PMID 23285167, 2012).
lymph node metastasis (1 paper, 2024). "When examining lymph node metastasis staging, the expression level of KRT81 was observed to be lower in the N3 stage compared to the N0 stage (p = .045)." (PMID 38778753, 2024).
tumor (28 papers, 2011 to 2025). "We noted a relative upregulation of specific luminal markers, KRT8 and KRT7, as well as distinctive expression of basal-like marker KRT81 in the migratory tumor subtype." (PMID 38892065, 2024). "In conclusion, this comprehensive study positions KRT81 as a promising prognostic marker for predicting tumor progression and immunotherapy responses in TNBC." (PMID 38778753, 2024). "In the unpaired analysis, the KRT81, KRT6A, and KRT17 genes, which were positively associated with FSTL3 expression, exhibited notably elevated expression in tumor tissues in comparison to that in normal tissues." (PMID 38240936, 2024). "Pairwise analysis revealed that tumor tissues exhibited significantly elevated expression of KRT81, KRT6A, KRT17, and KRT14, which were positively correlated with FSTL3 expression, compared to that in normal tissues." (PMID 38240936, 2024). "Gene annotation analysis indicated that KRT81 is involved in immune-related pathways and tumor cell adhesion." (PMID 38778753, 2024). "The low expression of GATA6 and high expression of the KRT81 genes in patient PDCA14 suggest that this tumor is squamous-like and therefore, a more aggressive subtype." (PMID 38968363, 2024). "A global proteome analysis and bioinformatic approach revealed the regulation of proteins involved in the formation of metastases, tumor cell invasion, and apoptosis, like keratin 81, CrkII, IL-1β, and cathepsin B." (PMID 38248645, 2023). "Hair keratin protein–KRT81, can downregulate inflammatory cytokine interleukin-8 to inhibit tumor progression." (PMID 36384635, 2022). "A more fine-grained analysis would benefit from a global, i.e., whole tumor quantitative analysis of KRT81 and HNF1a expression, which is currently unfeasible due to the necessity of whole tumor work-up." (PMID 32155990, 2020). "Distribution of clinical parameters between the cohorts with KRT81+ and KRT81- tumor subtypes alongside crosstabulation results." (PMID 31577805, 2019). "In only one case (DD439), a signal for CFTR and KRT81 was seen in immunohistochemical stainings of the primary tumor, whereas the corresponding organoid line only showed a high KRT81 expression on protein and mRNA level." (PMID 31191661, 2019). "A gradient-boosted-tree algorithm was trained on 70% of the patients (N = 28) and tested on 30% (N = 17) to predict KRT81+ vs. KRT81- tumor subtypes." (PMID 31577805, 2019). "Muckenhuber and colleagues suggest KRT81+ tumor cells to be more resistant to the FOLFIRINOX regimen compared to the exocrine-like subtype (HNF1A+)." (PMID 31191661, 2019). "It showed that KRT81 was highly correlated with tumor metastasis-related signaling pathways such as focal adhesion, ECM receptor interactions, and cell adhesion molecules, suggesting it may promote tumor metastasis." (PMID 38778753, 2024). "KRT81 could contribute to LUAD pathogenesis by affecting tumor cell mechanical properties, facilitating invasion and metastasis." (PMID 38596689, 2024). "Genetic deletion or reduction of KRT81 at the tumor site may enhance the efficacy of immunotherapy for TNBC." (PMID 38778753, 2024). "For example, the amplification of S100A4 and the amplification of KRT81 exhibit a co-occurrence relationship in both clusters, indicating that they have a common impact on tumor development and that there is a potential concomitant occurrence between the two genes." (PMID 37238637, 2023). "To answer the question if PDAC organoids express the same subtype-specific immunoreactivity as their corresponding primary tumor, we performed immunohistochemical stainings for KRT81 and CFTR on paraffin sections for all patients of which organoids were derived from resection specimens (n = 7)." (PMID 31191661, 2019). "To date, KRT81 has not been validated as a prognostic marker, and the present study is the first to link a KRT81 variant to tumor recurrence." (PMID 21799879, 2011).
tumor (continued). "Importantly, tumor recurrence was influenced by the SNP located in the 3′UTR of KRT81, the binding site of several miRNAs: miR-17, miR-93, miR-20b, miR-519d, miR-520g, miR-520h, miR-519c-3p, miR-519b-3p, miR-519a and miR-765." (PMID 21799879, 2011). "Our results indicated significant overexpression of GALNT2, MTHFD1, FAM207A, KRT81, and IKZF3 in tumor tissues, consistent with our bioinformatics analysis." (PMID 38596689, 2024). "Subclustering of natural killer (NK) cells revealed well-known NCAM1- and FCGR3A- expressing subsets and an interesting keratin (KRT81 and KRT86)-expressing subset potentially enriched in tumor tissues." (PMID 36423636, 2022). "Of these 7 survival-related genes, CSN3, KRT81, MUC7, and MYH6 has been elucidated to take part in tumor progression." (PMID 33530209, 2021). "Tumor microenvironment related genes ADGRG7, CSN3, CST8, KRT81, MUC7, MYH6, and SEZ6 are valuable predictors for HNSCC patient survival." (PMID 33530209, 2021). "Comparing the bulk transcriptome profiles of the TD and nonTD patients, the TD patients exhibited upregulation of keratins (KRT81, KRT6B, KRT15, KRT5) and kallikreins (KLK5, KLK6, KLK7), indicating active extracellular matrix (ECM) remodeling and tumor expansion." (PMID 39664386, 2024). "Notably, tumor cell lines with KRT81 knockdown demonstrated a diminished capacity to inhibit CD8 + T cells, suggesting that elevated levels of KRT81 promote an immunosuppressive microenvironment in TNBC." (PMID 38778753, 2024). "The molecular tumor subtype was defined by immunohistochemical staining for KRT81 and HNF1a as quasi-mesenchymal (QM) vs. non-quasi-mesenchymal (non-QM)." (PMID 32155990, 2020).
cancer (12 papers, 2011 to 2024). A tumor composed of atypical neoplastic, often pleomorphic cells that invade other tissues. "Among them, five genes (FGG, MYH15, STARD4, SYTL4, and TMEM267) were first associated with cancer procession, while the other three (KRT81, KRT6A, and KRT13) have previously been confirmed to be related to cancer metastasis and migration." (PMID 37817112, 2023). "Although expression of KRT81, a type II hair and nail keratin, has recently been shown to correlate with poor prognosis in a number of cancers, distinctions regarding the full‐length and truncated isoforms of these keratins are lacking." (PMID 37949677, 2024). "The results indicated that seven risk genes (SERPINE1, LAMC2, MYLK, IL21R, KRT81, MAMDC2, and PAEP) of the signature were differentially expressed in the cancer tissues compared to the normal tissues." (PMID 37636564, 2023). "KRT81, KRT6A, and KRT13 are examples of these genes that have been linked to cancer metastasis and migration in humans." (PMID 37817112, 2023). "Among them, three genes, i.e., KRT6A, KRT13, and KRT81, were related to cancer metastasis and migration." (PMID 37817112, 2023). "In the literature, KRT81 appears in numerous cancer studies." (PMID 37949677, 2024). "Furthermore, multiplex immunofluorescence for pancytokeratin (PanCK), MCT4 and KRT81, an established QM marker, in 6 PDAC FFPE specimens, showed that the proportion of MCT4-positive cells was higher among KRT81 positive (30–50%) than KRT81-negative cancer cells (< 20%)." (PMID 36494842, 2022).
KRT81 also shares sentences with these, for which no sentence is quoted: infection (14 papers); viral infection (5); pancreatic cancer (3); co-infection (2); malaria (2); acute myeloid leukemia (1); adenocarcinoma (1); adenosquamous carcinoma (1); bone metastasis (1); breast tumours (1); cervical cancer (1); epidermolysis bullosa simplex (1); gastric cancer (1); genetic disorders (1); hypotrichosis (1); mesothelioma (1); metastatic melanoma (1); non-Hodgkin lymphoma (1); non-small cell lung carcinoma (1); ovarian carcinoma (1); pachyonychia congenita (1); pancreatic adenocarcinoma (1); Pseudofolliculitis barbae (1); renal carcinoma (1); sarcoma (1); splenic marginal zone lymphoma (1); triple-negative breast carcinoma (1).